HMGB1 (high mobility group box 1)
Diseases named in the same sentence as HMGB1 in open-access papers (continued):
Sharing a sentence is not in itself a finding about the gene and the disease.
periodontal disease (5 papers, 2014 to 2025). "A significant increase (P < 0.05) was observed in the HMGB1 mRNA expression for both in vivo experimental periodontal disease models." (PMID 24692854, 2014). "Consistent with the in vitro findings, the in vivo data demonstrated an increase in HMGB1, at both mRNA and protein levels, within gingival tissues afflicted with experimental periodontal disease." (PMID 24692854, 2014). "In patients with periodontal disease, higher HMGB1 concentration and number of positive cells have been found, respectively, in gingival crevicular fluid and inflamed gingival epithelial cells compared to healthy control sites." (PMID 24692854, 2014). "As a result, more studies evaluating the effect of heat-killed bacteria or LPS from periodontopathogens are necessary to deeply investigate the role of HMGB1 in periodontal disease." (PMID 24692854, 2014). "As a result, HMGB1 plays a role in many acute and chronic inflammatory conditions, such as rheumatoid arthritis, diabetes mellitus, atherosclerosis, lupus, cancer, and periodontal disease." (PMID 24692854, 2014). "Immunohistochemical staining revealed that HMGB1 expression was increased during the course of periodontal disease in both models and was maintained from 7 d through 30 d." (PMID 24692854, 2014). "First, subclinical inflammation such as undiagnosed periodontal disease may have contributed to HMGB1 variability." (PMID 40557138, 2025). "In addition, this study evaluates in vivo the expression of HMGB1 during the initiation and progression of experimental periodontal disease induced in two rat models." (PMID 24692854, 2014). "Thus, HMGB1 is being expressed similarly and concomitantly with other cytokines during periodontal disease induction, suggesting a role of this molecule in the inflammatory events occurring in periodontal disease initiation and progression." (PMID 24692854, 2014). "Also, it is suggested that additional investigations evaluating the mechanisms of HMGB1 participation on periodontal tissue destruction in periodontal disease patients appear warranted." (PMID 24692854, 2014). "In addition, HMGB1 protein was detected by Western blot analysis at all time points for both periodontal disease models." (PMID 24692854, 2014). "More studies are necessary to investigate the role of HMGB1 in osteoclastogenesis during periodontal disease to better elucidate whether this protein has important participation, whether alone or in cooperation with other osteoclastogenesis-inducing signaling molecules." (PMID 24692854, 2014). "Also, the profile of HMGB1 expression during the initiation and progression of experimental periodontal disease was not evaluated yet." (PMID 24692854, 2014).
pulmonary tuberculosis (5 papers, 2010 to 2019). A bacterial infection that affects the lungs and is caused by Mycobacterium tuberculosis. "We aimed to study the pathogenic roles of High-Mobility Group Box 1 (HMGB1) / Receptor-for-Advanced-Glycation-End-products (RAGE) signaling and pro-inflammatory cytokines in patients with active pulmonary tuberculosis (PTB)." (PMID 27434276, 2016). "Since IFN-γ levels rise only after priming of adaptive immunity to Mtb its impact on HMGB1 release would most likely increase the immunopathology of pulmonary TB." (PMID 21072140, 2010). "We further investigated whether CSF HMGB1 level was a good biomarker to identify TBM in patients who suffered from extra neural tuberculosis such as pulmonary tuberculosis, intestinal tuberculosis, or joint tuberculosis." (PMID 27795917, 2016). "In the current study, we hypothesized that HMGB1/RAGE signaling and the pro-inflammatory cytokine responses play significant roles in pathogenesis and disease manifestations in patients with active pulmonary tuberculosis (PTB)." (PMID 27434276, 2016). "Indeed, one study showed that HMGB1/RAGE signaling may play an important role in pathogenesis and disease manifestations in non-HIV adults with active pulmonary TB." (PMID 30870511, 2019).
schistosomiasis (5 papers, 2011 to 2024). An infectious disease caused by parasitic trematodes of the genus Schistosoma that colonize human blood vessels and release eggs that can cause granulomatous reactions leading to acute (swimmer's itch or acute schistosomiasis syndrome) or chronic disease. "The results showed that the levels of IL-33 and HMGB1 in the sera of advanced schistosomiasis patients were significantly higher than those in the sera of healthy individuals (F = 4.55, 212.09, P < 0.05)." (PMID 38105713, 2024). "Clinically, HMGB1 presents a potential target for treatment of the chronic sequelae of schistosomiasis." (PMID 35335612, 2022). "Serum and liver levels of HMGB1 are significantly increased in some schistosomiasis patients with inflammatory responses, suggesting a close association with disease progression." (PMID 35335612, 2022). "HMGB1 is increased in the serum of patients with schistosomiasis and enables hepatic stellate cells to adopt a proliferative myofibroblast-like phenotype, which is crucial to schistosome-induced granuloma formation." (PMID 35335612, 2022). "In this study, we demonstrate elevated levels of HMGB1 in the sera in experimental mice or in patients with schistosomiasis." (PMID 30258438, 2018). "To investigate the role of HMGB1 during the course of schistosomiasis in a more controlled fashion, we infected BALB/c mice with 80 S." (PMID 30258438, 2018). "In this context, we also observed high levels of HMGB1 in the sera of patients from an endemic area in the State of Minas Gerais, Brazil, who suffer from acute or chronic schistosomiasis." (PMID 30258438, 2018). "In this study, we observed high levels of HMGB1 in the sera of mice with acute or chronic schistosomiasis, and the levels were slightly higher in the acute phase." (PMID 30258438, 2018). "Schistosome HMGB1 (SmHMGB1) is secreted by the eggs and stimulate the production of key cytokines involved in the pathology of schistosomiasis." (PMID 21887276, 2011). "Moreover, the potential collaboration of PZQ with HMGB1 inhibitors as a treatment for schistosomiasis should be explored." (PMID 35335612, 2022). "Because cytokine dysregulation is associated with increased mortality during schistosomiasis, we investigated whether GZR- or DIC-mediated inhibition of HMGB1 trafficking interfered with the cytokine expression profile during acute or chronic schistosomiasis." (PMID 30258438, 2018). "A direct involvement of HMGB1 signaling in the pathogenesis of schistosomiasis could be evoked with the use of a well-known HMGB1 direct inhibitor, Glycyrrhizin (GZR)." (PMID 30258438, 2018). "We next investigated the role of HMGB1 in the pathogenesis of schistosomiasis." (PMID 30258438, 2018). "Alternatively, after 56 days of infection, which characterizes the acute phase of schistosomiasis, an increased HMGB1 immunoreactivity was observed in the cytoplasm of hepatocytes around the granulomas of the infected untreated (IUT) and vehicle (VEH) control groups." (PMID 30258438, 2018). "Indeed, our animal survival curves showed an increased survival rate in mice under DIC administration, supporting the potential of HMGB1 inhibitors to treat schistosomiasis." (PMID 30258438, 2018). "High mobility group box 1 (HMGB1) is a multifunctional cytokine contributing to liver injury, inflammation, and immune responses in schistosomiasis by binding to cell-surface Toll-like receptors and receptors for advanced glycation end products." (PMID 35335612, 2022). "In addition, and importantly, a potential novel HMGB1 inhibitor, the 3-chloro-5-(4-pyridyl)-4,5-dihydroisoxazole (DIC) was tested in the model of schistosomiasis." (PMID 30258438, 2018). "Moreover, we show that inhibition of HMGB1 by DIC culminated in healthier hepatic parenchyma with reduced fibrosis, and small and individualized granulomas in murine schistosomiasis." (PMID 30258438, 2018).
silicosis (5 papers, 2018 to 2024). Silicosis is a respiratory disease caused by breathing in (inhaling) silica dust. "High levels of HMGB1 have been strongly linked to silicosis; each 1 ng/mL increase in plasma HMGB1 levels is positively correlated with an increased risk of silicosis." (PMID 38515835, 2024). "In agreement with previous studies, our results show that the elevated HMGB-1 level was significantly associated with higher odds of silicosis." (PMID 30558126, 2018). "In our study, we found that the increased HMGB-1 was significantly linked with collagen protein in the silicosis patients." (PMID 30558126, 2018). "Each 1 ng/mL increase in plasma HMGB-1 was significantly associated with increased odds of silicosis, and the odds ratio (OR) and (95% confidence interval (CI)) of silicosis was 1.86 (1.52, 2.27) after adjusting the potential confounders." (PMID 30558126, 2018). "Each 1 ng/mL increase in plasma HMGB-1 was positively associated with increased odds of silicosis, and the odds ratio (OR) (95% confidence interval) was 1.86 (1.52, 2.27)." (PMID 30558126, 2018). "Our results demonstrated that elevated plasma HMGB-1 was positivity associated with increased OR of silicosis." (PMID 30558126, 2018). "Accordingly, there is sufficient evidence to show that HMGB-1 is involved in the progression of silicosis, suggesting that it may represent a potential diagnostic biomarker and therapeutic target for silicosis." (PMID 38515835, 2024). "Second, we only observed the relationship between HMGB-1 and silicosis, but the underlying mechanisms are still unknown." (PMID 30558126, 2018). "Elevated plasma HMGB-1 concentrations were positively associated with increased odds of silicosis." (PMID 30558126, 2018). "In conclusion, we found that HMGB-1 was positivity associated with increased odds of silicosis." (PMID 30558126, 2018). "The increased secretion of HMGB1 can strongly promote leukocyte recruitment and activation, which triggers tissue repair and aggravates silicosis." (PMID 38515835, 2024). "HMGB-1 seems to be implicated in fibronectin and collagen-1 expression, suggesting that HMGB-1-mediated EMT contributes to the development of silicosis on day 28 and 84 after microcrystalline silica administration." (PMID 35889616, 2022). "HMGB1 and BRG1 are also highly expressed in the mouse silicosis model, and glycyrrhizic acid can inhibit the expression of HMGB1/BRG1 through the PI3K/Akt/mTOR pathway." (PMID 35886594, 2022). "Glycyrrhizic acid can affect the BRG1 and PI3K/Akt/mTOR pathway by inhibiting the expression of HMGB1 and delay the progression of silicosis in mice." (PMID 35886594, 2022). "In vivo, we injected glycyrrhizic acid into the mouse silicosis model to inhibit the expression of HMGB1." (PMID 35886594, 2022). "We observed that plasma HMGB-1 concentrations were significantly increased in silicosis patients when compared with healthy controls (p < 0.05)." (PMID 30558126, 2018). "Compared with healthy controls, the concentrations of plasma HMGB-1 were significantly increased in the silicosis (p < 0.05)." (PMID 30558126, 2018). "Compared with healthy controls, we found that the concentrations of plasma HMGB-1 >7.419 ng/mL had 81.6% sensitivity and 80.4% specificity for detecting silicosis, and the area under the curve (AUC) was 0.84." (PMID 30558126, 2018). "We further used ROC curve analysis to examine the discriminatory power of HMGB-1 in plasma for silicosis." (PMID 30558126, 2018). "A logistic regression model and receiver operating characteristic curve (ROC) analysis were performed to assess the relationships between HMGB-1 and silicosis." (PMID 30558126, 2018). "Compared with subjects in the low HMGB-1 levels, the OR of silicosis was 15.33 (6.70, 35.10) in those with higher plasma HMGB-1 after adjusting for potential confounders." (PMID 30558126, 2018). "Our results show that plasma HMGB-1 concentrations were significantly increased in silicosis patients when compared with healthy controls." (PMID 30558126, 2018).
silicosis (continued). "We found that the elevated plasma HMGB-1 concentrations were positively correlated with increased odds of silicosis." (PMID 30558126, 2018). "The pathophysiology behind the relationship between elevated HMGB-1 and silicosis is still unclear and likely complex." (PMID 30558126, 2018). "The objectives of this study were to explore the concentrations of plasma HMGB-1 in healthy controls and silicosis patients, and to investigate the relationships between plasma HMGB-1 levels and silicosis." (PMID 30558126, 2018). "Further studies are warranted to address the potential role of HMGB-1 in the screening and early diagnosis of silicosis." (PMID 30558126, 2018). "In ROC analyses, we found that plasma HMGB-1 >7.419 ng/mL had 81.6% sensitivity and 80.4% specificity for silicosis, and the area under the curve (AUC) was 0.84." (PMID 30558126, 2018). "Among the inhibitors targeting HMGB1, glycyrrhizic acid is the most widely used and the most effective, so this study chose glycyrrhizic acid as an intervention to explore its intervention effect and mechanism on experimental silicosis in mice." (PMID 35886594, 2022). "Glycyrrhizic acid is a new pharmacological inhibitor of HMGB1, which may inhibit the occurrence and development of silicosis." (PMID 35886594, 2022). "To explore whether glycyrrhizic acid affects the progression of silicosis by inhibiting the HMGB1-promoted EMT process, we performed further experiments." (PMID 35886594, 2022). "Additionally, compared with subjects with lower HMGB-1 concentrations, increased odds of silicosis were observed in those with higher HMGB-1 concentrations, and the OR was 15.33 (6.70, 35.10)." (PMID 30558126, 2018). "We further examined the relationships of plasma HMGB-1 with the stage of silicosis." (PMID 30558126, 2018). "In agreement with the previous studies, we found that HMGB-1 might be a potential biomarker for silicosis." (PMID 30558126, 2018). "In addition, to our knowledge, this study is the first to report the relationships between plasma HMGB-1 levels and silicosis in humans." (PMID 30558126, 2018). "However, epidemiological studies on the relationships between HMGB-1 and silicosis are still scarce." (PMID 30558126, 2018). "However, to determine whether HMGB-1 could be a new therapeutic or preventive biomarker for silicosis, further studies should be conducted." (PMID 30558126, 2018). "Our findings highlight that HMGB-1 may be a potential biomarker for silicosis." (PMID 30558126, 2018). "However, the role of HMGB-1 in silicosis is still uncertain." (PMID 30558126, 2018). "We found that plasma HMGB-1 concentrations were positively correlated with COL1A1 (r = 0.21, p < 0.05) among silicosis patients." (PMID 30558126, 2018). "To test this hypothesis, we constructed a silica-induced silicosis model and TGF-β1-induced EMT model, respectively, to determine the unknown relationship between HMGB1 and BRG1 and the role of glycyrrhizic acid in EMT-mediated PF." (PMID 35886594, 2022). "We speculate that glycyrrhizic acid inhibits the interaction between HMGB1 and BRG1 through the PI3K/Akt/mTOR pathway to affect the progression of silicosis." (PMID 35886594, 2022). "In addition, plasma HMGB-1 levels in stage III were significantly higher than those in the first and the second stages of silicosis (p < 0.05)." (PMID 30558126, 2018). "First, due to the lack of enrollment of healthy silica-exposed workers, we could not observe changes in HMGB-1 levels at early stages of silicosis and specify whether elevated plasma HMGB-1 concentrations are caused by the silica-dust exposure." (PMID 30558126, 2018). "Previous studies have shown that glycyrrhizin inhibits HMGB1 and thus inhibits EMT by blocking the downstream Smad2/3 signal pathway, but there is no study on glycyrrhizic acid in silica-induced silicosis in mice." (PMID 35886594, 2022).
skin inflammation (5 papers, 2018 to 2025). "In this study, we found that EVEs decreased skin inflammation by reducing HMGB1 and S100A8 and decreasing TLR4 expression, which then inhibited pyroptosis." (PMID 39684233, 2024). "The obtained outcomes shed light on the HMGB1 pathway as a potential therapeutic target in skin inflammation." (PMID 38001807, 2023). "Thus, we hypothesized that EVEs decrease skin inflammation by reducing HMGB1, S100A8, and the TLR4/NF-κB/NLRP3 inflammasome pathway, which eventually decreases TPA-induced skin inflammation." (PMID 39684233, 2024). "In the described study, dermatitis severity, histopathological changes, serum levels of IFN-γ and interleukin 4 (IL-4), and changes in the protein expression of HMGB1 were evaluated by Western blotting." (PMID 38001807, 2023). "To determine whether EVEs decreased the expression of the TLR4 ligands of HMGB1 and S100A8 in a mouse model of TPA-induced skin inflammation, we applied topical TPA to the right ear five times at 3-day intervals and measured the effects of the EVEs and DXA." (PMID 39684233, 2024).
spinal cord injury (5 papers, 2017 to 2026). Penetrating and non-penetrating injuries to the spinal cord resulting from traumatic external forces (e.g., WOUNDS, GUNSHOT; WHIPLASH INJURIES; etc.). "In addition, HMGB1 blockade has been reported to attenuate neuropathic pain in various preclinical models, suggesting that anti-HMGB1 mAb may also be beneficial in managing pain associated with spinal cord injury." (PMID 40943562, 2025). "Spinal cord injury (SCI) has been shown to trigger remote neuroinflammation in the frontal cortex via the HMGB1/TLR4/NF‐κB pathway, exacerbating neural damage and impairing functional recovery." (PMID 41555584, 2026). "After spinal cord injury (SCI) in humans, plasma HMGB1 levels in persons with acute SCI are significantly higher than in uninjured persons." (PMID 29178911, 2017). "In mice with spinal cord injury (SCI), high mobility group box1 (HMGB1) in DAMPs induces pro‐inflammatory microglia activation via the receptor for advanced glycation endproducts (RAGE)‐NF‐κB pathway, and inhibition of HMGB1 or RAGE significantly reduces neuronal loss and demyelination." (PMID 39915907, 2025).
spinal cord ischemia (5 papers, 2017 to 2025). Reduced blood flow to the spinal cord which is supplied by the anterior spinal artery and the paired posterior spinal arteries. "In addition, some studies have reported that DEX preconditioning effectively reduces the inflammatory response of myocardial, renal and spinal cord ischemia by downregulation of high-mobility group protein B1 (HMGB1)/toll-like receptor 4 (TLR4) pathways." (PMID 28729825, 2017). "Similarly, pro-inflammatory actions of hyperactivated HOTAIR have been reported to underlie inflammatory injury, oxidative damage, and cellular apoptosis in spinal cord ischemia–reperfusion injury, possibly in a high mobility group box 1 (HMGB-1)- and NF-κB-dependent manner." (PMID 38366205, 2024).
ST Elevation Myocardial Infarction (5 papers, 2012 to 2022). A myocardial infarction that produces elevation in the ST segments of the ECG. "Serum HMGB1 has been reported to be independently associated with increased mortality in patients with ST elevation myocardial infarction treated with PCI." (PMID 28950909, 2017).